CD14 (CD14 molecule)
Diseases named in the same sentence as CD14 in open-access papers (continued):
Sharing a sentence is not in itself a finding about the gene and the disease.
atherosclerosis (continued). "CD14, as an important mediator of inflammatory reactions, plays an important role in the process of immunity, inflammation, vascular endothelial dysfunction and atherosclerosis, which have a high risk of contributing to CAD." (PMID 33574831, 2020). "In addition, we have previously demonstrated that patients with familial hypercholesterolemia and thereby increased risk of atherosclerosis, had higher levels of both CD14+ MVs and CD14+CD36+ MVs compared to healthy controls." (PMID 30425991, 2018). "A recently longitudinal study showed ARID5B (transcription coactivator for histone H3K9me2 demethylation) CpG methylation is inversely associated with both ARID5B expression and atherosclerosis in human CD14+ blood monocyte, while the associations vanished in T cell samples from the same subset." (PMID 29410709, 2018). "We hypothesized that genetic susceptibility to H. pylori infection is associated with the risk of atherosclerosis and aimed to evaluate risk factors for atherosclerosis according to the CD14 polymorphism in healthy subjects with H. pylori infection." (PMID 24228026, 2013). "In our results, the specific genotype of CD14 gene seems to have the risk of atherosclerosis." (PMID 24228026, 2013). "Moreover, genetic factors for the development of atherosclerosis would be associated with the LPS-mediated activation processes of monocytes and their receptor CD14." (PMID 24228026, 2013). "Therefore, the CD14 polymorphism is a good candidate for assessing the genetic effect of atherosclerosis development at a relatively early phase." (PMID 24077340, 2013). "The TLR4 Asp 299Gly SNP and CD14 -159C/T SNP, rather than either SNP separately, was found to be associated with clinically relevant atherosclerosis suggesting that the CD14 -159C/T SNP may influence heart disease only in concert with variation in other genes." (PMID 23730203, 2012). "Interestingly, increased presence of CD14+CD16+ cells is commonly associated with inflammatory diseases such as Atherosclerosis, Kawasaki disease or bacterial infection and LRRK2 participates to antibacterial responses." (PMID 21738687, 2011). "In both murine and human models of atherosclerosis, CD14+CD16−CCR2+ monocytes are expanded and exhibit increased trafficking to atheromatous plaques." (PMID 41301673, 2025). "CD14 is primarily expressed on monocytes, which play an important role in the initiation and progression of atherosclerosis, and therefore have gained considerable interest as a potential biomarker for predicting cardiovascular events." (PMID 40495286, 2025). "Previous studies have demonstrated the importance of the interactions between CD14 and the proatherogenic factors in the development of atherosclerosis." (PMID 40002707, 2025). "It is important to consider that the role of the monocytes in the atherosclerosis is strongly influenced by both surface markers CD14 and CD16, as well as their ratio." (PMID 40002707, 2025). "This was performed in CD14+ monocytes, a cell-type critical in atherosclerosis pathology, via fine particulate matter collectively termed PM2.5 and Oxides of nitrogen (NOX) in the Multi-Ethnic Study of Atherosclerosis (MESA) study (n ~ 1.2 k)." (PMID 38602535, 2024). "The CD14-positive subpopulation was decreased upon NP and NG treatment, respectively, improving the inflammation aspects of atherosclerosis." (PMID 37620556, 2023). "An increase in the absolute number of TLR4-positive intermediate monocytes (CD14++CD16+TLR4+) was also found in patients with polyvascular atherosclerosis progression—479.0 cells/μL (388.0–543.0) versus 761.0 cells/μL (273.2–466.5), p = 0.0099." (PMID 37569579, 2023). "This study used immunomagnetically sorted CD14+ cell gene expression microarray data from the Multi-Ethnic Study of Atherosclerosis (MESA, n = 1202, GSE56047) and the Correlated Expression and Disease Association Research (CEDAR, n = 281, E-MTAB-6667) cohorts." (PMID 37371794, 2023).
atherosclerosis (continued). "Emerging evidence showed that CD14 is a multitalented receptor, which was distinctly involved in the pathogenesis of inflammation, atherosclerosis, tumor, and metabolic diseases." (PMID 35308143, 2022). "In this study, we provided a perspective for understanding the roles of CD14+ monocytes in the development of the calcification paradox in osteoporosis- and atherosclerosis-related cells based on combined scRNA and RNA data." (PMID 35937796, 2022). "Our work provides a perspective for understanding the triggering roles of CD14+ monocytes in the development of the calcification paradox in osteoporosis- and atherosclerosis-related cells based on combined scRNA and mRNA data." (PMID 35937796, 2022). "We noticed that most (76.49%) common scRNA-based CD14+ monocyte markers between osteoporosis and atherosclerosis were upregulated in the CD14+ circulating monocytes from osteoporosis and atherosclerosis patients." (PMID 35937796, 2022). "It has been reported that macrophage polarization plays a key role in the progression of atherosclerosis, so we tested the expression of marker proteins (CD14, CD86, and CD206) by Western blot." (PMID 36159969, 2022). "CD14 promotes atherosclerosis by regulating the function of vascular endothelial cells and smooth muscle cells." (PMID 34233597, 2021). "For example, CD14 macrophages are found in complicated atherosclerotic lesions, and atherosclerosis progression delays when Nox2 (an essential component of NADPH oxidase) is inhibited in animal models." (PMID 34829669, 2021). "This decrease of the CD14+CD16+ monocytes noted during weight loss was associated with a decrease in the intima-media thickness and hence a reduced risk in atherosclerosis." (PMID 32528415, 2020). "This role must take the greatest importance at the severe stages of atherosclerosis, judging by the correlation links between frequency of CD14++CD16lo monocytes and hsCRP in patients with stenosis >70%." (PMID 33854919, 2020). "We found a direct association between CD14 CD16hi monocytes and concentration of CXCL16,+ which goes in accordance with their controversial role in atherosclerosis." (PMID 33854919, 2020). "CD14+ inflammatory monocytes are known to drive atherosclerosis and increase cardiovascular events in humans." (PMID 31608057, 2019). "In comparison to the apparent association between intermediate CD14++CD16+ monocytes and cardiovascular events due to atherosclerosis, its relationship to metabolic disorders seems weak." (PMID 29582352, 2018). "In contrast to findings from the Malmo Diet and Cancer study, others have reported CD14++CD16+ monocyte subsets to have a greater contribution in the pathogenesis of atherosclerosis." (PMID 30572572, 2018). "BLTR1+ MVs and CD14+CD36+ MVs has potential as markers of atherosclerosis pathophysiology, but this needs further investigation." (PMID 30425991, 2018). "VB-201, an oxidized phospholipid mimic which is orally available, binds to TLR2 and CD14 to limit downstream inflammatory pathways and has beneficial effects on atherosclerosis and experimental autoimmune encephalomyelitis." (PMID 29515999, 2018). "Here, the authors examine CD14+ blood monocyte’s transcriptome and epigenome signatures to find differential methylation and expression of ARID5B to be associated with human atherosclerosis." (PMID 28855511, 2017). "CD14+CD16+ monocytes are potent secretors of IL-1, IL-6 and TNF-α, and expanded CD14+CD16+ monocyte populations are found in inflammatory disease states including atherosclerosis, obesity and rheumatoid arthritis." (PMID 28494757, 2017). "The binding of LPS monomers to soluble CD14 expressed by endothelial cells induces cytokine production and atherosclerosis through the Toll-like receptor 4 signaling pathway." (PMID 25286027, 2014). "Previously, it has been reported that acute myocardial infarction/atherosclerosis are more closely related to CD14 −159TT homozygotes." (PMID 24228026, 2013).
atherosclerosis (continued). "Similarly, according to findings from the multiethnic study of atherosclerosis (MESA), increments in the classical CD14++CD16− monocytes are associated with declining of systolic blood pressure levels." (PMID 39273110, 2024). "Furthermore, it had been observed that the treatment with anti-CCR5 antibody was able to inhibit the entry of CD14+CD16++ monocytes into plates in an experimental model of atherosclerosis." (PMID 36741809, 2022). "To test this hypothesis, we performed live staining of the mitochondria of CD14+ monocytes from healthy donors and atherosclerosis patients with MitoTracker Orange CMTMRos dye, which is sensitive to mitochondrial membrane potential." (PMID 33557383, 2021). "We speculate that inflammation may be induced by CD14, resulting in immune dysfunction and endothelial dysfunction leading to atherosclerosis." (PMID 33574831, 2020). "We did not observe changes in the pro-inflammatory CD14++ monocytes which is consistent with another a study showing that CD14++CD16− monocytes do not associate with atherosclerosis measured as CC-IMT in subjects without CV acute events." (PMID 31299986, 2019). "Soluble CD14 reflects monocyte activation and bacterial translocation, and had also been associated with subclinical atherosclerosis in PLWH, but not with ischemic morbidity." (PMID 31026289, 2019). "Increasing experimental evidence is suggesting that rs2569190A>G in the CD14 promoter could contribute to the genetic etiology of human atherosclerosis." (PMID 31671579, 2019). "In fact, the elevated numbers of CD14++CD16+ monocytes have been reported to be an independent predictor of cardiovascular events, suggesting a profound association between CD14++CD16+ monocytes and atherosclerosis." (PMID 29582352, 2018). "Neither the surrogates of residual cell contamination nor the % of CD14+ CD16+ cells was associated with the measures of atherosclerosis." (PMID 28855511, 2017). "MiR-155, enriched in CD14+ monocytes, was closely related with inflammation and could pleiotropically regulate atherosclerosis." (PMID 28961259, 2017). "Previously, specific genotype of CD14 gene may favor increased inflammation in atheroma, promoting possible worsening atherosclerosis." (PMID 24228026, 2013). "However, since CD14 levels are generally reduced in patients with advanced atherosclerosis, the observed increase in CD14 expression might have a beneficial effect on the atherosclerotic process." (PMID 40002707, 2025). "CD14 is a pro-inflammatory cytokine that activates NF-κB and MAPK pathways and importantly has been linked to the development of arterial wall inflammation seen in atherosclerosis, a process which is also similarly seen in the spiral arteries of patients with PE." (PMID 40464837, 2025). "This supported the relationship between an increased Lp(a) level and multiple vessel atherosclerosis as Lp(a) causes endothelial dysfunction and damage through different mechanisms, one of them being increased non-classical CD14+CD16++ monocytes in patients with hyper Lp(a)." (PMID 39734983, 2024). "In the atherosclerosis dataset GSE28829, CD14 (AUC = 0.938), C1QB (AUC = 0.947), CD53 (AUC = 0.952), LY96 (AUC = 0.904), P2RX7 (AUC = 0.981), C3 (AUC = 0.817), and TNFSF13B (AUC = 0.875) demonstrated favorable diagnostic efficiency for differentiating patients with atherosclerosis from controls." (PMID 37649719, 2023). "We also cannot address the association of IDOL in CD14+ monocytes with atherosclerosis." (PMID 37094639, 2023). "Interestingly, IPA analysis demonstrated that the most significantly altered microRNAs in CD16+ monocytes exhibited a prevalence of target mRNAs involved in atherosclerosis, while only half of those microRNAs in CD14+ monocytes had target mRNAs related to atherosclerosis." (PMID 31169830, 2019).
atherosclerosis (continued). "Our study shows for the first time that increased atherosclerosis risk in T1DM patients associates with decreased expression of CDKN2A/2B/2BAS in leukocytes, which display pro-atherogenic phenotypes consisting of reduced circulating Treg cells and augmented proinflammatory CD14++ CD16+ monocytes." (PMID 31299986, 2019). "Thus, CD14 was considered to be a key role in the process of atherosclerosis and complications." (PMID 30922395, 2019). "However, longer longitudinal studies are required to establish what might be the role of CD14+/endoglin+ cells in the process of atherosclerosis in patients with hypertension." (PMID 29304136, 2018). "Our data suggest that, JNK1 may, via the activation of AP1 family, activate the transcriptional machinery of CD14 and SR-AI genes to increase their expression, which in turn contributes to oxLDL uptake in macrophages/foam cell formation, resulting in atherosclerosis." (PMID 29354064, 2017). "In order to evaluate whether pattern recognition receptors (PRRs) such as TLR-4 and CD14 contribute to atherosclerosis formation, we genotyped both study and control groups for the Asp299Gly and Thr399Ile polymorphisms of the TLR-4 gene and the C260T CD14 gene polymorphism." (PMID 29367560, 2016). "In addition, we cannot definitely show whether the increase in CD14+ monocytes precedes the development of atherosclerotic lesions, or whether it results from inflammatory conditions in atherosclerosis." (PMID 25668619, 2015). "Ultimately, a Venn diagram pinpointed CD14 and RNASE1 as the distinctive characteristic genes for atherosclerosis, derived from the intersected findings of the three modeling techniques." (PMID 39364414, 2024). "Focusing on these studies would not only benefit RA patients but also shed light on other diseases where CD14++ CD16+ macrophages play a significant role, such as atherosclerosis." (PMID 38785736, 2024). "For instance, some proteins related to atherosclerosis were down-regulated in SF, such as ARG2, CD14, CD44, engulfment, and cell motility protein 1 (ELMO1), neutrophil gelatinase-associated lipocalin (LCN2), MPO, S100A8, or S100A9." (PMID 34572333, 2021). "Significantly, the levels of a number of highly-expressed mRNAs in both CD14+ and CD16+ monocytes of RA patients correlated with atherosclerosis severity, as assessed by carotid intima media thickness ratio." (PMID 32582174, 2020). "Thus, the relationship that C-159T whether dependent on rs2569190 to alter the activity of CD14 gene promoter affect CD14 gene expression and lead to atherosclerosis, increase the risk of CAD, was not to be researched." (PMID 30922395, 2019). "The PCR array showed a specific and differential expression profile of genes related to atherosclerosis in CD16+ and CD14+ monocytes from RA patients compared to HDs." (PMID 31169830, 2019). "The search terms (including their derivatives, i.e., plural) were monocyte, monocyte subset, CD14, CD16, exercise, atherosclerosis, atherosclerosis plaque, cardiovascular disease, coronary artery disease, and vascular epithelium." (PMID 30572572, 2018). "These included proteins involved in atherosclerosis/inflammation (e.g. GDF-15, lipopolysaccharide binding protein, and CD14), extracellular matrix [matrix metalloproteinase-7 (MMP7)], heart failure [N-terminal pro-B-type natriuretic peptide (NT-proBNP)], and renal insufficiency cystatin C (CST3)." (PMID 39660078, 2024). "Flow cytometric analysis revealed high levels of IL1RAP on CD11b+CD14+ macrophages, suggesting that this population may be a key target for IL1RAP blockade in atherosclerosis." (PMID 38563353, 2024). "CD14++CD16− produces low levels of tumor necrosis factor alpha (TNF-α) and high amount of IL-10, whereas CD14+CD16++ secretes high levels of pro-inflammatory cytokines promoting atherosclerosis." (PMID 37600028, 2023).
atherosclerosis (continued). "Our findings suggest a novel pro-inflammatory mechanism that involves CD14 shedding through enhanced Akt/PRAS40 activation, which may explain the increase in macrophage inflammatory responses in diabetes-accelerated atherosclerosis." (PMID 37237950, 2023). "However, in humans, their CD14+ CD16+ cell counterpart has been reported to increase in many noninfectious diseases, such as coronary arterial disease, atherosclerosis, hemophagocytic syndrome, and cancer." (PMID 36310859, 2022). "CD14+ blood monocyte transcriptome and epigenome signatures suggest that ARID5B expression, possibly regulated by an epigenetically controlled enhancer, promotes atherosclerosis by dysregulating immunometabolism towards a chronic inflammatory phenotype." (PMID 35534881, 2022). "Besides, another metabolite, LPS, involved in infectious diseases has recently shown to have some effects on atherosclerosis based on in experimental and clinical trials by binding to various proteins, such as LBP, CD14, TLR-4, and MD-2." (PMID 34414217, 2021). "In addition to IFN-α, several triggers of atherosclerosis, including thrombin and IFN-γ, can induce CMPK2 expression, which was elevated in CD4+ T cells and CD14+ monocytes isolated from SLE patients compared to those isolated from controls." (PMID 33874983, 2021). "Moreover, CD14 and TLR4 play a vital role in initiating sterile inflammation related to atherosclerosis." (PMID 34829669, 2021). "Although the expression of CD11b and CD14 is significant, Nobuhiko and colleague mentioned in one of their animal studies that it is not essential in the development of atherosclerosis." (PMID 33761885, 2021). "In addition to IFN-α, several triggers of atherosclerosis, including thrombin and IFN-γ, can induce CMPK2 expression, which is elevated in CD4+ T cells and CD14+ monocytes isolated from SLE patients compared to those isolated from controls." (PMID 33874983, 2021). "Monocytes are recognized as central cells in the progression of atherosclerosis, and are subcategorized into classical (CD14++CD16lo), intermediate (CD14++CD16hi) and non-classical (CD14+CD16hi) subsets." (PMID 33854919, 2020). "Intermediate monocytes (CD14++CD16+) are known to participate in atherosclerosis but we discovered that HCMV-specific IgG did not affect the level of intermediate monocyte, indicating a different mechanism for monocyte activation in ESRD patients." (PMID 29988679, 2018). "Moreover, CD14++CD16+ monocytes secrete high levels of tumor necrosis factor-α and interleukin-1β, which are involved in the pathogenesis and progression of atherosclerosis." (PMID 28789689, 2017). "Intermediate CD14++CD16+ monocytes selectively express C–C chemokine receptor type 5 (CCR5), secret more inflammatory cytokines such as tumor necrosis factor-α and interleukin-1β, and have been shown to drive atherosclerosis." (PMID 28789689, 2017). "Only the decrease in “non-classical” CD14+CD16++ monocytes in advanced disease stages was more profound in patients suffering from generalized atherosclerosis compared to patients suffering from PAOD only." (PMID 27991581, 2016). "Moreover, the CD14+ cells showed increased CDK9 levels in atherosclerotic plaques, which indicated the role of CDK9 in monocyte infiltration during atherosclerosis." (PMID 26636538, 2016). "Similarly, in human patients there was a small, but statistically significant, CD14++CD16− inflammatory subset preponderance at 48 h (82.9 ± 6.9% vs. 75.9 ± 5.1% (P < 0.001), compared with control patients with stable atherosclerosis." (PMID 25982896, 2015). "Further exploration of the relationship between intermediate (CD14++CD16+) monocytes and atherosclerosis will significantly advance our understanding of pro-atherogenic conditions and aide in the design of novel cell-directed therapies for the treatment of atherosclerosis." (PMID 25852821, 2015).